PELP1 (proline, glutamate and leucine rich protein 1)
Diseases named in the same sentence as PELP1 in open-access papers (continued):
Sharing a sentence is not in itself a finding about the gene and the disease.
cancer (continued). "In fact, published studies utilizing knock down approaches, blockage of PELP1 downstream signaling utilizing a KDM1A inhibitor, and reducing PELP1 expression using a CDK inhibitor Roscovitine, demonstrate the benefit of targeting PELP1 in reducing cancer progression." (PMID 37199805, 2023). "In addition, we utilized an in vivo animal model system to augment the clinical significance of PELP1 in inflammation and cancer progression." (PMID 34774800, 2022). "Localization and/or post-translational modifications of PELP1 in both normal and cancer tissue could play roles in mediating SR coactivation." (PMID 36351913, 2022). "In addition, animal studies demonstrated the connection of PELP1 in inflammation-directed cancer progression." (PMID 34774800, 2022). "Our results from in vivo studies established a strong proof showing PELP1 as one of the critical molecules that may function as a link between inflammation and cancer." (PMID 34774800, 2022). "PELP1 is as a scaffolding oncogenic protein in a variety of cancer types, but its involvement in angiogenesis is unknown." (PMID 35053547, 2022). "In addition, elevated PELP1 expression was positively associated with advanced tumor stage, advanced stage, and lymph node metastasis, consistent with the role of PELP1 identified in other cancers." (PMID 32117782, 2019). "PELP1 was localized predominantly in the nuclei of carcinoma cells in TNBC." (PMID 26472563, 2015). "In addition, CARM 1 and PELP1 are transcriptional corepressors and indicators of reduced disease free survival in luminal cancers." (PMID 24392136, 2014). "Of the 63 cancer tissues, 48 (76.2%) of patients were found to express nuclear staining of PELP1." (PMID 23497172, 2013). "In conclusion, our results show that PELP1 expression, alone and in combination with ERbeta, may be an interesting research target in this cancer entity." (PMID 23497172, 2013). "Collectively, these findings suggest that PELP1 functions as an oncogenic scaffold that integrates NR signaling, cytoplasmic kinase pathways, chromatin remodeling, and ribosome biogenesis, positioning it as a central regulator of transcriptional and translational programs in cancer." (PMID 41463382, 2025). "In addition, PELP1’s distinct localization, widespread post-translational modifications, and ability to form discrete signaling complexes contribute to its diverse effects on cancer cell proliferation, survival, and therapeutic resistance." (PMID 41463382, 2025). "Interestingly, engineered clones of BCa cells expressing cytoplasmic PELP1 are tumorigenic in vivo, promote apototic sensitivity changes, and are estrogen-independent, highlighting the role of PELP1 subcellular localization in cancer progression." (PMID 41463382, 2025). "In a recent study, glutamic acid-, proline-, and leucine-rich protein 1 (PELP1) was found to be a novel ER coregulator, which has shown distinct characteristics from other ERα coregulators, and has recently been shown to play a role in the metastasis of several types of cancer." (PMID 37764733, 2023). "To identify whether GM-CSF secreted from PELP1 overexpression clones of RAW 264.7 cells has any impact on cancer transformation, we used concentrated and filter-sterilized conditioned media (CM) collected from PELP1 overexpression clones of RAW 264.7 cells for functional studies." (PMID 34774800, 2022). "Hence, targeting PELP1 appears to be a promising strategy for cancer treatment." (PMID 34522213, 2021). "Proline-, glutamic acid-, and leucine-rich protein 1 (PELP1), a coregulator of estrogen receptors alpha and beta, is a potential protooncogene implicated in several human cancers, including sexual hormone-responsive or sexual hormone-nonresponsive cancers." (PMID 24967003, 2014).
cancer (continued). "In this study, we tested the hypothesis that deregulation of PELP1 promotes activation of KDM1-driven epigenetic modifications at ERα target genes contributing to cancer proliferation/therapy resistance by testing the therapeutic effect of targeting the PELP1-KDM1 axis." (PMID 22812534, 2012). "PELP1 interacts with AIB1 (NCOA3)-containing complexes, and such interactions are shown to promote advanced cancer phenotypes." (PMID 41463382, 2025). "They found that their peptidomimetic, named D2, was able to specifically disrupt the binding of PELP1 to AR with an IC50 of 40 nM, preventing AR translocation, resulting in decreased growth of cancer cells in vitro, in vivo, and ex vivo." (PMID 40023399, 2025). "To explain feedback regulation of PELP1 in inflammation-driven cancers, we incubated mouse mammary epithelial cell line, HC11, with CM collected from PELP1 overexpression clones of RAW 264.7 cells." (PMID 34774800, 2022). "From this, 15 genes were found to be essential in all TNBC cell lines including some of the well-known regulators of cancer cell fitness, such as UHRF1, PELP1 and PRMT1." (PMID 35973998, 2022). "Well-known cancer survival genes such as PELP1 and PRMT family members were identified as common hits in all the six cancer cell lines screened by EPIKOL." (PMID 35973998, 2022). "ESR1 Cr values strongly positively correlated with ESR2 Cr only in unchanged tissue and was moderately correlated with both PELP1 Cr and SRC Cr in cancer affected tissue." (PMID 34207568, 2021). "The ER coregulator PELP1 modulates epigenetic changes on ER target gene promoters via interactions with KDM 1, and KDM1 inhibitors are currently in clinical trials for other cancers." (PMID 34528025, 2021). "Only in cancer affected tissue, ESR1/SRC and ESR2/PELP1 ratios were both positively correlated with PELP1/SRC (moderately strong) and ESR2/SRC (strong), respectively." (PMID 34207568, 2021). "In the present study, the oncogenic function of the ER coregulator PELP1 or NMAR was identified in CRC, a common and highly invasive type of cancer." (PMID 24967003, 2014). "Our earlier studies indicated that the proto-oncogene PELP1 promotes KDM1-driven epigenetic modifications leading to local estrogen synthesis, contributing to cancer cell proliferation and therapy resistance." (PMID 22812534, 2012). "PELP1 modulates genes that are involved in the epithelial–mesenchymal transition (EMT), including MMPs, SNAIL (SNAI1), TWIST (TWIST1), ZEB (ZEB1), MYC, MTA1, miR-200a, and miR-141, leading to cancer metastasis progression." (PMID 41463382, 2025). "While there are clear indications of PELP1's involvement in cancer proliferation and progression, its precise impact on cancer development via ribosome biogenesis, rather than hormone receptor activity regulation, remains largely unexplored." (PMID 38633862, 2024). "Proline-, glutamic acid-, and leucine-rich protein 1 (PELP1) is a scaffolding protein with no known enzymatic activity that functions as a proto-oncogene in several cancers including BC." (PMID 37199805, 2023). "PELP1 might regulate the expression of the miR-200 family and bind to CAGE to exert its effect on the responses of cancer cells to anti-cancer drugs." (PMID 35682560, 2022). "Since CAGE could bind to HDAC2 in anti-cancer drug-resistant melanoma cells, it will be interesting to examine whether CAGE could bind to PELP1." (PMID 35682560, 2022).
cancer (continued). "The status of PELP1 immunoreactivity in LUAD was significantly higher than that in the NTL tissues and significantly positively correlated with less differentiated features of carcinoma cells, positive lymph node metastasis, higher clinical stage as well as the status of ERα, ERβ, and PCNA." (PMID 34257530, 2021). "Moreover, some researchers determined the oncogenic functions of PELP1 in hormone-non-responsive cancers, such as brain tumor, lung cancer, and colorectal cancer." (PMID 32117782, 2019). "We speculated oncogenic function of PELP1 in hormone-nonresponsive cancers did not depend on estrogen receptor α and β." (PMID 32117782, 2019). "Therefore, PELP1 can be regarded as a therapeutic target in hormone-nonresponsive cancers." (PMID 24967003, 2014). "ESR2/SRC ratio was positively, very strongly correlated with PELP1/SRC ratio in tissue lack of any changes and strong in cancer affected tissue." (PMID 34207568, 2021). "In case of ESR2 Cr, cancer affected tissue showed a significant negative correlation with ESR1/ESR2 ratio (moderately strong) and positive with both ESR2/PELP1 (very strong) and ESR2/SRC (moderately strong)." (PMID 34207568, 2021). "This study is the first to identify the oncogenic function of PELP1 in CRC, a hormone-nonresponsive cancer." (PMID 24967003, 2014). "Interestingly, the ESR1/ESR2 ratio was characterized by a strong, negative correlation with ESR2/PELP1 ratio in OCP, and moderately strong with ESR2/SRC ratio in both benign changes of ovary and cancer affected tissue." (PMID 34207568, 2021).
tumor (33 papers, 2012 to 2025). "Cytoplasmic PELP1 expression is associated with increasing the number of ALDH tumor spheres in a BCa model." (PMID 41463382, 2025). "Higher PELP1 protein expression is associated with various features, including higher tumor grade, increased proliferation, node-positive invasive disease, distant metastases, and reduced BCa-specific factors as well as disease-free survival." (PMID 41463382, 2025). "Significantly higher PELP1 was associated with tumors of higher grade with regard to the tumor differentiation, lymph node metastasis and clinical stage of the patients." (PMID 34257530, 2021). "In this study, higher PELP1 expression was associated with tumors of higher grade with regard to tumor differentiation, lymph node metastasis, and clinical stage." (PMID 34257530, 2021). "Previously, we reported that PELP1 expression is associated with larger tumours and clinicopathology features indicative of poor prognosis, including high grade and basal cytokeratin expression." (PMID 24392136, 2014). "According to DepMap and cBioPortal, PELP1 LOH is associated with haploinsufficiency in many tumours, raising the possibility that del17p might confer increased sensitivity to the PELP1 degrader, SMIP34." (PMID 39966556, 2025). "Although, the presence of association cannot establish causality, this may indicate that tumor PELP1 is regulated by estrogen in these patients." (PMID 26247365, 2015). "In NSCLC, PELP1 is overexpressed, which exacerbates tumor cell malignancy and resistance to tyrosine kinase inhibitor drugs." (PMID 41463382, 2025). "PELP1 expression is positively correlated with advanced tumor stage and lymph node metastasis in GCa." (PMID 41463382, 2025). "PELP1 tumor levels are correlated with estogen levels in normal tissues and plasma in postmenopausal women." (PMID 41463382, 2025). "LPS/c-Rel drives PELP1 expression in macrophages; PELP1 overexpression triggers granulocyte–macrophage colony-stimulating factor (GM-CSF) secretion, resulting in tumor progression via the microenvironment." (PMID 41463382, 2025). "Quantitation of IHC staining showed that PELP1 expression is significantly higher in ECa tumor tissues compared to normal tissues." (PMID 37853941, 2024). "We utilized the TNMplot analysis tool, which enables the comparison of gene expression between tumor and normal tissues to examine alterations in PELP1 levels in HCC." (PMID 39258975, 2024). "Analyses of data from the Clinical Proteomic Tumor Analysis Consortium using the UALCAN tool revealed that the expression of PELP1 is higher in HCC tumors compared with normal liver tissues." (PMID 39258975, 2024). "Administering PELP1-siRNA liposomes to xenograft tumors resulted in a substantial decrease in tumor volume." (PMID 39258975, 2024). "Supporting our STRING analysis, a study of the AR interactome showed that PELP-1 and β-catenin were significantly upregulated in PCa tumour compared to normal tissue." (PMID 39671399, 2024). "PELP1-KD in Hep3B cells led to a notable decrease in tumor volume and weights compared with control Hep3B xenografts, indicating that PELP1-KD hinders the progression of HCC tumors." (PMID 39258975, 2024). "Here, we used EEC cell lines, organoids, tumor tissues, and xenograft animal models to examine the impact of blocking PELP1 oncogenic signaling on the progression of the EEC subtype of ECa." (PMID 37853941, 2024). "Previous studies found that treatment of xenograft tumors with PELP1-siRNA liposomes significantly reduced tumor volume." (PMID 37199805, 2023). "Our results reveal the specific function of PELP1 in promoting angiogenesis, thus to facilitate tumor metastasis." (PMID 35053547, 2022). "Most of the previous studies showed that PELP1 promoted tumor metastasis by enhancing tumor invasion and migration ability." (PMID 35053547, 2022). "The results showed that ribosome and c-Myc target gene signatures were enriched in PELP1-high tumor samples in comparison with PELP1-low samples." (PMID 35205680, 2022).
tumor (continued). "To investigate the role of PELP1 on tumor angiogenesis in vivo, we inoculated HCT116-shCtrl and HCT116-shPELP1 cells into flanks of nude mice." (PMID 35053547, 2022). "In this study, our results indicated that PELP1 was up-regulated in CRC tissues compared with normal colorectal specimens, and that inhibition of PELP1 led to inhibition of tumor growth." (PMID 35053547, 2022). "Our results using bioinformatic analyses of TNBC gene expression data sets identified that ribosome and c-Myc-target gene signatures were enriched in PELP1-high tumor samples compared to PELP1-low tumor samples." (PMID 35205680, 2022). "To confirm the effect of PELP1 KD on tumor formation during inflammation, we injected 4T1 clones into the mammary fat pads, stimulated with Nec-HC11 in female BALB/c (immunocompetent) mice." (PMID 34774800, 2022). "In this study, we found that tumor vessels normalization can be induced by inhibition of PELP1 in CRC." (PMID 35053547, 2022). "A recent study explained that cytoplasmic PELP1 induces secretion of inflammatory cytokines into a protumorigenic microenvironment through NF-κB, which promotes tumor initiation." (PMID 34774800, 2022). "The present study revealed that the high expression of PELP1 is closely related with angiogenesis in CRC.We proved that PELP1 promotes tumor angiogenesis by activating the STAT3 pathway." (PMID 35053547, 2022). "A plenitude of data describes the role of PELP1 in tumor development, but limited investigation has been carried out on unraveling its role in inflammation-driven oncogenesis." (PMID 34774800, 2022). "PELP1 displays its function as a key coregulatory protein offering tumor cells with a specific growth and survival preference by modulating proliferation, migration, invasion, metastasis, and endocrine resistance." (PMID 34774800, 2022). "In our study, for the first time, we illustrated the mechanism of transcriptional regulation of PELP1 during inflammation and identified the downstream molecular targets of PELP1 responsible for inflammation to tumor transformation." (PMID 34774800, 2022). "Concomitantly, treatment of BC xenografts with PELP1‐siRNA liposomes significantly reduced tumor volume." (PMID 33269540, 2021). "Further analysis confirmed that PELP1 expression was positively correlated with tumor stage and grade; PELP1 expression was closely related to tumor differentiation." (PMID 32117782, 2019). "Further, ERX-11 treatment group had lower ER but similar PELP1 protein expression levels within the tumor, compared to control." (PMID 28786813, 2017). "The authors demonstrated that the protein levels of ERβ and its co-activators, TIF2, AIB1 and PELP1, fluctuate as tumor grade increases in astrocytomas and are correlated with clinical and histopathological parameters." (PMID 29113424, 2017). "In all patients, tumor PELP1 correlated with normal tissue concentrations of E1 and E2 (r = 0.366, P = 0.020 and r = 0.329, P = 0.038, respectively)." (PMID 26247365, 2015). "Taken together, the positive correlations between PELP1 and estrogen levels in tumor, normal tissue and circulation seem to be exclusive to estrogen responsive ER+ tumors only." (PMID 26247365, 2015). "Specifically, PELP1 overexpression has been reported to induce the malignant transformation of normal cells, accelerate cell cycle progression, promote tumor cell proliferation, and enhance the migration and invasion of tumor cells." (PMID 26472563, 2015). "In previous in vitro studies, reduction of PELP1 expression by RNA interference (RNAi) exhibited a substantial inhibitory effect on proliferation, invasion, and therapeutic resistance of tumor cells." (PMID 26472563, 2015). "We found PELP1 tumor levels in postmenopausal patients to be positively associated with estrogen levels in normal tissue and plasma." (PMID 26247365, 2015). "Further, we conducted analyses in two tumor subgroups, ER+ and ER-, and examined potential correlations of PELP1 with estrogens." (PMID 26247365, 2015).